FKBP6 (FKBP prolyl isomerase family member 6 (inactive))
Description:
Has an essential role in spermatogenesis. It is required to repress transposable elements and prevent their mobilization, which is essential for the germline integrity (By similarity). Acts via the piRNA metabolic process, which mediates the repression of transposable elements during meiosis by forming complexes composed of piRNAs and Piwi proteins and govern the methylation and subsequent repression of transposons (By similarity). Acts as a co-chaperone via its interaction with HSP90 and is required for the piRNA amplification process, the secondary piRNA biogenesis (By similarity). May be required together with HSP90 in removal of 16 nucleotide ping-pong by-products from Piwi complexes, possibly facilitating turnover of Piwi complexes (By similarity).
Synonyms: FKBP36; PPIase; SPGF77
Tractability: Small molecule: it belongs to a druggable protein family.
Gene: Protein-coding gene on chromosome 7 (73,328,161 to 73,358,637, forward strand). Ensembl gene ENSG00000077800.
Subcellular location: Cytoplasm; Nucleus
Subcellular location (Human Protein Atlas): Cytosol; Nucleoli fibrillar center; Cytokinetic bridge; Microtubules
Pathways (Reactome):
Gene expression (Transcription): PIWI-interacting RNA (piRNA) biogenesis
Reproduction: Meiotic synapsis
Gene Ontology:
Molecular function: identical protein binding; protein binding; FK506 binding; Hsp90 protein binding; peptidyl-prolyl cis-trans isomerase activity
Biological process: positive regulation of viral genome replication; meiotic cell cycle; piRNA processing; protein folding; regulatory ncRNA-mediated gene silencing; spermatogenesis; transposable element silencing by piRNA-mediated DNA methylation
Cellular component: cytoplasm; cytosol; fibrillar center; nucleus; synaptonemal complex
Genetic constraint (gnomAD): Loss-of-function variants: 21 observed, 28.3 expected, observed/expected ratio (o/e) 0.74, 90% interval 0.52 to 1.07. The upper end of that interval is the gene's LOEUF score, 1.07, which puts it in group 4 of 6, group 1 being the genes least tolerant of losing a copy. Missense variants: 278 observed, 330.98 expected, observed/expected ratio (o/e) 0.84, 90% interval 0.76 to 0.93. Synonymous variants: 110 observed, 135.08 expected, observed/expected ratio (o/e) 0.81, 90% interval 0.7 to 0.95.
Homologues: Orthologues: chimpanzee FKBP6 (99% identical), chimpanzee FKBP6 (95% identical), dog FKBP6 (89% identical), pig FKBP6 (88% identical), rat Fkbp6 (83% identical), mouse Fkbp6 (82% identical), macaque FKBP6 (74% identical), tropical clawed frog fkbp6 (59% identical), zebrafish fkbp6 (49% identical), Drosophila melanogaster shu (28% identical), Caenorhabditis elegans fkb-4 (10% identical), Caenorhabditis elegans fkb-5 (9% identical). Paralogues in human: FKBP5 (23% identical), FKBP8 (23% identical), FKBP4 (22% identical), FKBP15 (20% identical), FKBPL (16% identical), FKBP9 (14% identical), FKBP10 (13% identical), FKBP14 (12% identical), TTC9 (12% identical), FKBP7 (11% identical), TTC9C (11% identical), TTC9B (10% identical), and 6 more.
Diseases named in the same sentence as FKBP6 in open-access papers:
FKBP6 is named in the same sentence as 14 diseases in open-access papers, as found by Europe PMC text mining. Sharing a sentence is not in itself a finding about the gene and the disease. The quoted sentences say what the papers report.
male infertility (4 papers, 2010 to 2012). The inability of the male to effect fertilization of an ovum after a specified period of unprotected intercourse. "Therefore, an association of the FKBP6 gene with human male infertility cannot be excluded." (PMID 21054846, 2010). "Functionally, FKBP6 encodes a member of FK506 binding protein family and has been associated with male infertility in humans and mice, while TRIM56 belongs to tripartite motif-containing gene family, members of which, like TRIM36 (alias HAPRIN), are involved in acrosome reaction of mammalian sperm." (PMID 23284302, 2012). "The involvement of FKBP6 in male infertility in mice and humans further strengthened the hypothesis." (PMID 23284302, 2012). "In mice, targeted deletions of the genes coding for FKBP6 or FKBP52, members of the FK506 binding protein family, can result in male infertility." (PMID 20210997, 2010). "These functional categories contained several genes playing a role in spermatogenesis, fertilization, and determination of the testicular mass, some of which are involved in human and murine male infertility (DDX25 and FKBP6) (SPAG6)." (PMID 20576090, 2010).
Williams syndrome (4 papers, 2012 to 2025). "In human patients with Williams syndrome carrying a large multi-gene deletion on chromosome 7q11.23, FKBP6 hemizygocity was found to contribute to hypercalcemia and growth retardation." (PMID 26025256, 2015). "Genomic organization, expression profile and domain structure of FK506-binding protein 6 (FKBP6) were first described in humans in connection with Williams syndrome." (PMID 23284302, 2012). "FKBP6 is associated with the Lipin 3 (LPIN3) gene and the RAD9 checkpoint clamp component A (RAD9A) gene and has been associated with Williams syndrome and Williams-Beuren syndrome, but FKBP6 does not have an advantage in terms of the strength of association with the target disease." (PMID 34966851, 2021).
Azoospermia (3 papers, 2010 to 2012). Absence of any measurable level of sperm,whereby spermatozoa cannot be observed even after centrifugation of the semen pellet. "The WBS deletion includes the gene FKBP6 which has recently been shown to play a role in male reproduction, showing azoospermia in knockout mice." (PMID 21054846, 2010). "There are reports showing that FKBP6 mutations do not cause azoospermia, and those suggesting that FKBP6 single nucleotide transitions play a modifying role in the susceptibility to idiopathic spermatogenic impairment." (PMID 23284302, 2012). "In humans mutations in the FKBP6 gene does not appear to cause azoospermia." (PMID 21054846, 2010). "The FKBP6 (alias FKBP36) protein is a component of synaptonemal complex and plays a critical role in male meiosis due to which FKBP6 knockout male mice and rats are sterile with azoospermia, whereas females are reproductively normal." (PMID 23284302, 2012). "In infertile men, no mutations of FKBP52 or FKBP6 have been found so far, but the gene for FKBP-like (FKBPL) maps to chromosome 6p21.3, an area linked to azoospermia in a group of Japanese patients." (PMID 20210997, 2010).
cervical cancer (1 paper, 2021). A primary or metastatic malignant neoplasm involving the cervix. "It was reported that promoter methylation of FKBP6 can be used as a biomarker for the diagnosis of cervical cancer." (PMID 34887898, 2021).
hepatoma (1 paper, 2015). "HCV replication was completely suppressed in FKBP6-knockout hepatoma cell lines, while the expression of FKBP6 restored HCV replication in FKBP6-knockout cells." (PMID 26567527, 2015).
tumor (2 papers, 2015 to 2021). "We found that the FKBP gene family had a higher overall expression level in all tumor samples except FKBP6." (PMID 34476212, 2021). "Expression of the FK506 binding proteins FKBP4, FKBP6, and FKBP9, immunophilins known to interact with mTOR, was upregulated in DC-tumor fusions 5.3-, 6.7-, and 28-fold." (PMID 26605345, 2015).
FKBP6 also shares sentences with these, for which no sentence is quoted: cardiac hypertrophy (1 paper); Cognitive impairment (1); glioma (1); Hypercalcemia (1); infertile (1); lung carcinoma (1); polycystic kidney disease (1); Tinnitus (1).